PRL (prolactin)
Diseases named in the same sentence as PRL in open-access papers (continued):
Sharing a sentence is not in itself a finding about the gene and the disease.
systemic lupus erythematosus (continued). "To explore whether the formation of TFH cells may be influenced by PRL, we determined the expression pattern of the PRL receptor between lupus-prone and control mice, reporting the expression of the PRL receptor as the fold change in TFH cells with respect to that of 9-week-old Tnaïve cells." (PMID 33763492, 2021). "Serum levels of prolactin and estradiol are usually increased significantly during pregnancy, puerperium, or postpartum lactation period compared to normal women, which indicated that high serum levels of prolactin and estradiol might contribute to lupus flares." (PMID 25973434, 2015). "Therefore, the aim of this study was to determine whether developing bone marrow B cells express the PRL receptor and whether development is altered in response to PRL sera levels that correlate with the onset of lupus in a murine model of this disease." (PMID 24454471, 2013). "In this study, our aims were to determine the level of PRL receptor expression during bone-marrow B-cell development and to assess whether the presence of high PRL serum concentrations influences absolute numbers of developing populations and disease outcome in lupus-prone murine models." (PMID 24454471, 2013). "The objective of this study was to characterize the participation of prolactin in the differentiation and activation of TFH cells, by performing in vivo and in vitro tests with lupus-prone mice, using flow cytometry and real-time PCR." (PMID 33763492, 2021). "It is important to note that patients with systemic lupus erythematosus (SLE) are especially prone to developing macroprolactinemia due to the presence of anti-prolactin antibodies; an estimated one-third of patients with SLE and hyperprolactinemia were found to have macroprolactinemia." (PMID 31367466, 2019). "The aim of this work was to determine the effect of PRL in an in vitro system of B-cell tolerance using WEHI-231 cells and immature B-cells from lupus prone MRL/lpr mice." (PMID 27314053, 2016). "C57BL/6, MRL and MRL/lpr mice treated with metoclopramide showed a further increase in their serum PRL levels that was only accompanied by increased levels of anti-dsDNA antibodies and proteinuria in the MRL/lpr and MRL lupus-prone strains." (PMID 22404893, 2012). "In addition, PRL activity was more prominent in MRL/lpr immature B cells, since in the lupus-prone strain only, the inhibitors significantly reduced pSTAT3." (PMID 33557010, 2021). "In addition, the PRL activity was more prominent in MRL/lpr TFH cells, since the inhibitor significantly reduced pSTAT3 only in the lupus-prone strain." (PMID 33763492, 2021). "This problem is broader, as autoimmune diseases generally affect women more often, which is explained by the influence of estrogen and prolactin, which have an immunomodulatory effect on the proliferation of autoreactive B lymphocytes in SLE (systemic lupus erythematosus)." (PMID 32824462, 2020). "In addition to high levels of prolactin, low levels of DHEA were detected in the serum of lupus patients." (PMID 26583155, 2015). "In addition to high levels of prolactin and low levels of DHEA, results from this study revealed a significant increase in serum estradiol in lupus patients (p = 0.0003)." (PMID 26583155, 2015). "Prolactin gene expression levels were also higher in PBMCs from lupus patients (p = 0.0017) compared to nonlupus controls." (PMID 26583155, 2015). "This study further demonstrated that the lupus cohort in this study had a higher serum level of prolactin in their PBMCs in comparison to age-matched nonlupus patients." (PMID 26583155, 2015). "This is particularly so in systemic lupus erythematosus (SLE), where it is thought that prolactin may even play a role in its pathogenesis." (PMID 25431724, 2014). "Indeed, targeting local PRL expression, potentially via topical application of a PRLR antagonist, could represent an elegant treatment option for skin manifestations of lupus." (PMID 39000207, 2024).
systemic lupus erythematosus (continued). "Furthermore, PRL bolsters the development of lupus-like phenotype in non-prone mice and exacerbated the disease in a lupus murine experimental study." (PMID 29483903, 2018). "However, the −1149GT (p = 0.1503) and −1149GG (p = 0.1480) genotypes did not significantly correlate to any differences in prolactin gene expression levels in PBMCs from lupus patients when compared to age-matched nonlupus patients." (PMID 26583155, 2015). "Conversely, treating mice with an antagonist of the secretion of PRL (bromocriptine) decreased the absolute number of these cells with respect to mice treated with PBS or without treatment; this behavior was only observed in lupus-prone mice." (PMID 33763492, 2021).
peripartum cardiomyopathy (41 papers, 2010 to 2025). Peripartum cardiomyopathy (PPCM) is an idiopathic, potentially fatal form of dilated cardiomyopathy that develops during the final month of pregnancy or within five months after delivery. "Generation of cardiotoxic subfragments of prolactin caused by oxidative stress has been implicated in peripartum cardiomyopathy in women." (PMID 28224564, 2017). "In cardiac ECs from women affected with peripartum cardiomyopathy (a life-threatening pregnancy-associated cardiac pathology), the cathepsin D-cleaved 16-kDa N-terminal prolactin fragment upregulates the expression of miR-146." (PMID 26742038, 2016). "Notably, prolactin’s association with peripartum cardiomyopathy (PPCM) is significant, as it may induce endothelial cell apoptosis, vasoconstriction, and impair cardiomyocyte function, potentially leading to PPCM28." (PMID 40021736, 2025). "Significant insights into the pathophysiological mechanisms underlying peripartum cardiomyopathy have been provided by the theory of an abnormal 16-kDa prolactin, which may be generated in an oxidative stress environment and lead to vascular and consequently myocardial damage." (PMID 39408885, 2024). "Lastly, as expected, no relation of PRL to arrhythmias was shown; in fact, the only association between PRL and the heart exists in the pathogenesis of peripartum cardiomyopathy, where a small antiangiogenic subfragment, 16-kDa prolactin, may provoke the disease by inducing endothelial damage." (PMID 34833372, 2021). "For example, plasma prolactin levels are elevated in conditions such as the acute phase of myocardial infarction, ischemic stroke, and transient ischemic attack, hypertension and preeclampsia, while evidence suggests a causative role of prolactin in postpartum cardiomyopathy." (PMID 33396861, 2020). "In peripartum cardiomyopathy, cleavage of prolactin into its 16 kDa fragment exerts toxic anti-angiogenic effects, while in pre-eclampsia, overexpression of sFlt-1 disrupts VEGF- and PlGF-mediated endothelial repair." (PMID 41300945, 2025). "The inhibition of prolactin release using the dopamine antagonist, bromocriptine, prevents the development of peripartum cardiomyopathy in mice, suggesting a potential role of prolactin in the pathogenesis of the disease." (PMID 38464847, 2024). "Recently, bromocriptine, a prolactin release inhibitor has been explored as a therapeutic option in peripartum cardiomyopathy." (PMID 38464847, 2024). "These mice displayed features of peripartum cardiomyopathy, which was reversed by bromocriptine, a prolactin inhibitor." (PMID 37109553, 2023). "Myocardial STAT3 levels are reduced, and serum levels of activated cathepsin D and 16 kDa prolactin are elevated in patients with peripartum cardiomyopathy." (PMID 37109553, 2023). "Bromocriptine can be used to treat peripartum cardiomyopathy by reducing the harmful cleaved prolactin fragments during late pregnancy." (PMID 37109553, 2023). "There have been new findings in the research related to pathogenesis behind peripartum cardiomyopathy making way for prolactin inhibition as a treatment modality." (PMID 35382200, 2022). "Prolactin inhibition, as a treatment option for peripartum cardiomyopathy, remains a topic of controversy worldwide with differences of opinion regarding its safety and its placement in the standard treatment protocol." (PMID 35382200, 2022). "Regarding endothelial cells, it was shown that in peripartum cardiomyopathy, a cardiac disease initiated by a cleaved prolactin fragment (16-kDa N-terminal prolactin fragment, 16K PRL), increased expression of miR-146 hampering angiogenesis." (PMID 33013428, 2020). "In particular conditions such as peripartum cardiomyopathy, ECs, stimulated by 16-kDa N-terminal prolactin fragment (16K PRL), overexpress miRNA-146a that exerts anti-angiogenic and anti-proliferative effects on ECs." (PMID 30781555, 2019).
peripartum cardiomyopathy (continued). "A recent report showed that the Vi derived from PRL mediate peripartum cardiomyopathy (PPCM), which is defined as heart failure presenting between the last month of pregnancy and 5 months after delivery in mothers with no history of heart failure." (PMID 28163696, 2017). "It is considered that Vi derived from PRL are involved in the pathogenesis of peripartum cardiomyopathy (PPCM)." (PMID 28163696, 2017). "The prolactin fragment is involved in the pathogenesis of peripartum cardiomyopathy exhibiting anti-angiogenic and proapoptotic effects on the myocardium." (PMID 26742038, 2016). "It was determined that cathepsin D is the major prolactin cleaving enzyme in peripartum cardiomyopathy." (PMID 25007941, 2014). "The role of an altered form of prolactin in the pathophysiology of peripartum cardiomyopathy has been explored of late in animal models." (PMID 22924131, 2012). "Recently, the overexpression of 16–kDa prolactin was suggested to be a possible physiopathological mechanism for peripartum cardiomyopathy." (PMID 22567052, 2011). "Consistent with this idea, blockade of prolactin by bromocriptine, a dopamine D2–receptor agonist, prevented the onset of disease in an experimental model of peripartum cardiomyopathy and appeared successful in small pilot trials." (PMID 22567052, 2011). "A small pilot study suggested that prolactin blockade by bromocriptine in addition to standard therapy prevents repeated episodes of peripartum cardiomyopathy in patients presenting with a subsequent pregnancy." (PMID 20202212, 2010). "Recently, oxidative stress-mediated generation of anti-angiogenic and pro-apoptotic 16 kDa prolactin and subsequent impaired cardiac microvascularisation have been related to peripartum cardiomyopathy." (PMID 20202212, 2010). "It has been hypothesized that elevated prolactin levels may be a critical factor in the pathophysiology of peripartum cardiomyopathy." (PMID 41244055, 2025). "The identification of a biological substrate may lead to the identification of novel therapeutic targets such as prolactin in peripartum cardiomyopathy." (PMID 38308002, 2024). "Circulating levels of the antiangiogenic protein vasoinhibin, a fragment of prolactin, are of interest in vasoproliferative retinopathies, preeclampsia, and peripartum cardiomyopathy; however, it is difficult to determine the circulating levels of vasoinhibin due to the lack of quantitative assays." (PMID 38742198, 2024). "Through removing the cleaved form of prolactin despite activating the cleaving enzyme, bromocriptine, a dopamine agonist that decreases prolactin production, may improve outcomes in patients with peripartum cardiomyopathy." (PMID 37629345, 2023). "However, CTSD yields a cleaved 16-kDa form of prolactin, which has antiangiogenic and proapoptotic properties, and contributes to postpartum cardiomyopathy." (PMID 32176724, 2020). "A seminal study in 2007 introduced the hypothesis that an antiangiogenic prolactin fragment with a molecular mass of 16 kDa is a key pathological mediator of peripartum cardiomyopathy (PPCM)." (PMID 28443067, 2017). "Thus, in pregnant PGC-1α knockout mice, the 16 kDa prolactin-induced antiangiogenic effect and the inhibition of proangiogenic factors act together towards the development of a very severe form of peripartum cardiomyopathy." (PMID 25007941, 2014). "While investigating the mechanistic basis of peripartum cardiomyopathy, it was found that a fragment of prolactin (16K PRL) could induce the expression of miR-146a in endothelial cells, leading to inhibition of angiogenesis." (PMID 25429310, 2014). "Different treatment modalities are available in order to treat peripartum cardiomyopathy ranging from general considerations such as salt restriction to the use of drugs such as diuretics, β blockers, vasodilators, anticoagulants, and more recently, prolactin inhibitors." (PMID 35382200, 2022).
peripartum cardiomyopathy (continued). "Future study in this regard may uncover exciting results given the involvement of prolactin in the pathology of the peripartum cardiomyopathy, and the interference of prolactin and melatonin in the processes responsible for the development and maintenance of pregnancy." (PMID 30037127, 2018). "The aetiology of peripartum cardiomyopathy has been unclear for many years; however, new research into an inflammatory or immunological basis, and the role of prolactin in the development of the disease has shed new light on the causative mechanisms that may be behind this condition." (PMID 22924131, 2012). "Intra-aortic balloon pump (IABP) was inserted on postpartum day (PD) 10 with a peripartum cardiomyopathy (PPCM), which was withdrawn on PD 30 after medical treatment including anti-prolactin drugs." (PMID 34725740, 2021). "A dysregulation of the generation of vasoinhibin hormones by proteolytic cleavage of prolactin (PRL) has been brought into context with diabetic retinopathy, retinopathy of prematurity, preeclampsia, pregnancy-induced hypertension, and peripartum cardiomyopathy." (PMID 29163363, 2017). "Blocking miR-146a with a specific antagomir causes the attenuation of peripartum cardiomyopathy clinical features in STAT3 conditional knockout mice, without affecting full-length prolactin-dependent milk production functions." (PMID 25007941, 2014).
Gynecomastia (40 papers, 1975 to 2025). Abnormal development of large mammary glands in males resulting in breast enlargement. "In the United States, Johnson & Johnson compensated risperidone users with up to US$8 billion due to gynecomastia, which can occur due to increased prolactin levels associated with risperidone use." (PMID 40802386, 2025). "While gynecomastia can develop in patients with hyperprolactinemia, the condition arises secondary to the gonadotropin suppression prolactin can cause." (PMID 36644692, 2022). "Among AAS users there is the belief that AAS might cause gynecomastia through alternative pathways, such as increased progestin action at the mammary glands or increased prolactin levels." (PMID 36644692, 2022). "Furthermore, Weydt and colleagues, in 2011, reported a few cases of gynecomastia due to the consumption of venlafaxine and fluoxetine, which were all associated with increased prolactin levels." (PMID 30123864, 2018). "Gynecomastia can be prevented by constantly monitoring prolactin levels, as described in clinical protocols and international guidelines." (PMID 40802386, 2025). "Overall, prolactin (PRL) plays a significant role in pubertal gynecomastia (PG) by disrupting hormonal balance and enhancing breast tissue sensitivity." (PMID 39797240, 2024). "Mieritz’s study found strong PRL receptor positivity in immunohistochemical staining of surgical specimens from 39 PG patients, indicating that prolactin may play a role in gynecomastia." (PMID 39797240, 2024). "Finally, MTX can promote gynecomastia by blocking the activity of IL-1, which has been shown to influence pituitary hormone secretion, including prolactin." (PMID 39518594, 2024). "In general, high prolactin levels (≧20 ng/ml) are uncommon in patients with gynecomastia." (PMID 39735055, 2024). "Despite the lack of any evidence or even theoretical basis for this practice, some AAS users self-medicate with dopamine agonists such as bromocriptine and cabergoline to lower their assumed increased prolactin levels and treat their ‘prolactin-induced’ gynecomastia." (PMID 36644692, 2022). "Moreover, an excess of gynecomastia in the ticagrelor PLATO arm (0.19% vs. 0.03%, RR = 6.0) suggests prolactin involvement, and estrogen burst to increase the size of male breast tissue." (PMID 34300305, 2021). "According to latest recommendations, each patient suspected of gynecomastia on physical examination without an identified cause, should undergo hormonal investigation including determination of blood LH, FSH, PRL, TTE, E2, beta-hCG and TSH." (PMID 31117335, 2019). "Although estrogen is deeply involved in the development of gynecomastia and in the creation of lactation period-like changes in the mammary glands, the involvement of other hormones, including progesterone, androgen, and prolactin cannot be ruled out." (PMID 26101734, 2015). "However, his hormone levels (prolactin, beta-hCG, testosterone, E2, LH, FSH, T3, T4) were within normal range, and no gynecomastia or tumor was found in breast." (PMID 23531415, 2013).